MMP9 (matrix metallopeptidase 9)
Diseases named in the same sentence as MMP9 in open-access papers (continued):
Sharing a sentence is not in itself a finding about the gene and the disease.
melanoma (continued). "The observed increase in MMP2 and MMP9 activity as well as other alterations in extracellular matrix and adhesion molecule expression suggested that BRG1 plays an important role in regulating melanoma invasiveness." (PMID 20969766, 2010). "Human melanoma invasion involved MMP-1, MMP-2, MMP-9 and MT1-MMP." (PMID 20959825, 2010). "The most extensively studied MMPs in melanomas are MMP-2 and MMP-9." (PMID 20631829, 2010). "It has been demonstrated that invasive melanoma cell lines show higher MMP-9 expression and higher activity when compared to non-invasive cell lines." (PMID 17346338, 2007). "In primary melanomas, MMP-9 is variably expressed in radial but not in the vertical growth phase and the de novo expression seems associated with early invasion." (PMID 17346338, 2007). "Consequently, targeting MMP-2 and MMP-9 may offer therapeutic potential for inhibiting EMT and metastasis in melanoma The MMP-9’s enzymatic breakdown of ECM barriers modulates the tumor microenvironment to facilitate metastasis." (PMID 41394861, 2025). "In addition, downregulated expression of MMP-2 and MMP-9 with concomitant increased expression of tissue inhibitors of metalloproteinases TIMP-1 and TIMP-2 has also been observed in the luteolin-treated A375 melanoma cells." (PMID 37687080, 2023). "In the quickly proliferating melanoma A375 cell line, the expression levels of apoptotic protein BCL-2 and invasion-related MMP9 were significantly increased, while KYNU could promote the increased expression of MMP9 and AMPK." (PMID 35893303, 2022). "Moreover, melanoma xenografts obtained inoculating mouse melanoma cells into mouse ischemic limbs, showed an increase in vasculogenic mimicry under ischemic condition, and higher expression of HIF-1α, VEGF, matrix metalloproteinases 2 (MMP2), and MMP9." (PMID 33964953, 2021). "But the effect is not specific to colon cancer cells because much the same activity was reported using A375 and B16 melanoma cells, with an inhibition of cell proliferation, induction of caspase-dependent apoptosis and inhibition of cell migration due to inhibition of MMP-2 and MMP-9." (PMID 33534099, 2021). "We can also mention the case of the C–O–C type biflavone ochnaflavone which inhibits MMP-9 secretion in human aortic smooth muscle cells through the transcription factors NFκB and AP-1 or a derivative of agathisflavone which suppresses MMP-2 expression and reduces metastasis of melanoma cells." (PMID 33534099, 2021). "DLC-1 is a Rho GTPase-activating protein (RhoGAP), could facilitate melanoma cell invasion and metastasis by cooperating transcription factor FOXK1 to promote MMP9 expression and enhancing colorectal cancer metastasis by the epithelial-to-mesenchymal transition." (PMID 33682883, 2021). "Since we showed a greater inhibitory effect of the FB/SFN combination on cell migration in the metastatic WM266-4 cell line, we evaluated if SFN and FB could alter the production of collagenase MMP-1, gelatinases MMP-2 and MMP-9 and stromelysin MMP-3 in this melanoma cell line." (PMID 32486135, 2020). "Moreover, since B16.F1 melanoma cells show low metastatic capability, whether the final outcome of these opposite effects in migration and MMP-2 and MMP-9 activities would be pro- or anti-metastatic needs to be addressed." (PMID 33202705, 2020). "Chromatin immunoprecipitation (ChIP) assay confirmed a higher binding affinity of FOXK1 for the consensus motif within the MMP9 promoter in melanoma cells compared with IgG control, whereas it did not bind to another DNA fragment without the motif, indicating the specificity of the binding." (PMID 32214200, 2020). "Although we could not detect spontaneous brain and lung metastases in our model, our results show that activity of MMP-2 and MMP-9 and angiogenesis were decreased in tumors developed in TNFR1 KO mice, suggestive of a pro-tumoral role of TNFR1 in melanoma progression." (PMID 33202705, 2020).
melanoma (continued). "Indeed, a previous study showed that acidic pH promotes experimental pulmonary metastasis of human melanoma cells in athymic nude mice by up-regulating the expression of the proteolytic enzymes MMP-2, MMP-9, cathepsin B, and cathepsin L and the proangiogenic factors VEGF-A and IL-8." (PMID 30836626, 2019). "Moreover, fisetin treatment resulted in downregulation of MMP-2 and MMP-9 (data not shown) in monolayer and 3-D melanoma cultures (Sup." (PMID 30356079, 2018). "Furthermore, melanoma cells use MMP9 noncatalytic functions to sustain rounded‐amoeboid invasion via regulation of actomyosin contractility." (PMID 28085224, 2017). "Therefore, CoQ0 may inhibit melanoma metastasis through the suppression of MMP-2, and MMP-9 expression." (PMID 26968952, 2016). "First of all, our results confirmed the over expression of hMMP-9 in melanoma tumors and were well correlated with the binding intensities of 111In-F3B-DOTA even if the anti-hMMP-9 antibody used for immunostaining was raised against the mouse MMP-9 with lower specificity compared to the aptamer F3B." (PMID 26901393, 2016). "In addition, cordycepin was able to decrease the expression of MMP-2, MMP-9 and CD44 and suppress cell motility, suggesting that cordycepin not only regulates early stages of melanoma metastasis, but also late stages of melanoma dissemination, such as adhesion and extravasation." (PMID 25868853, 2015). "Gelatinase B/MMP-9 knockout mice also exhibit substantial inhibition of spontaneous metastasis due to impaired triggering of the “angiogenic switch”, and in experimental metastasis models, lung metastasis formation by both melanoma and lung carcinoma cells is reduced." (PMID 24473089, 2014). "However, MMP9 is detected only in VGP melanoma, not in RGP tumors." (PMID 33430277, 2021). "In contrast to melanoma cell lines, M2 macrophages stimulated by LL-37 in vitro significantly increased their expression and secretion of MMP-1, but not MMP-9 expression." (PMID 36980564, 2023). "We demonstrated that melanoma CM, but not primary melanocyte CM, were able to induce the PMN release of MPO and MMP-9, known angiogenic and pro-tumorigenic factors." (PMID 37525065, 2023). "PCDH9 and CCND1 (Cyclin D1) exhibited a positive correlation, whereas MMP2, MMP9, and RAC1 exhibited a negative correlation with both melanoma A375 and G361 cells." (PMID 36452505, 2022). "This was consistent with the immunodetection of MMP-9 and MMP-3 in melanoma cells located into the dermis, but not those localized in the epidermis." (PMID 32455575, 2020). "Accordingly, metastatic, but not primary, melanoma cells secreted large amounts of a MMP, presumably MMP-9." (PMID 24905466, 2014). "An in vitro study on mouse melanoma cells found that triphenylphosphine oxide (TPPO), a selective TRPM5 blocker, dose-dependently inhibited acidic pHe-induced matrix metalloproteinase-9 (MMP-9) production (IC50: 41 mM after 24 h), but did not reduce cell viability." (PMID 40227837, 2025). "We could show that while advanced-melanoma patients responding to targeted therapy were characterized by higher pretreatment MPO levels, the pretreatment MMP-9, HGF and IL-8 levels were similar in both responders and nonresponders." (PMID 38730718, 2024). "Melanoma and CRC cell migration was affected in a dose-dependent fashion as observed through scratch assay, whereas the secretion of matrix degrading proteins metalloprotease 2 (MMP2) and 9 (MMP9) in tumor cells did not significantly change." (PMID 36297277, 2022). "Although SIM exerts suppressive effects on expression and activation of MMPs52 and on melanoma cell migration capacity when co-administered with DMXAA9, our data suggested no significant modulation of MMP-2 and MMP-9 lytic activity by either LCL-SIM or LCL-DMXAA (P > 0.05)." (PMID 34764332, 2021).
melanoma (continued). "Because knockdown of MMP-9 did not alter Madcam1 protein levels, and Madcam1 silencing did not affect MMP-9 protein expression, we conclude that the effects were independent, and that both proteins are needed for metastatic dissemination of melanoma cells." (PMID 31600735, 2019). "Moreover, GAS5 attenuates the expression and the activity of MMP2 and MMP9 and has a role in regulating the metastasis phenotype of melanoma cells; however, no data are published about the role of GAS5 as a regulator of MMP9 and MMP2 expression in IBD patients." (PMID 31652976, 2019). "Fibronectin also induces gelatinase B/MMP-9 expression in ovarian cancer cells through FAK and ras activation and laminin has been shown to up-regulate gelatinase B/MMP-9 expression in macrophages and in A2058 melanoma cells but not in other malignant tumour cells." (PMID 24473089, 2014).
lung carcinoma (415 papers, 2003 to 2026). "These target genes of miR-21-5p are implicated in lung cancer progression and are involved in the upregulation of MMP-9, an endopeptidase that modulates the TME." (PMID 41240165, 2025). "Elevated SP abundance was significantly associated with increased MMP-9 expression, advanced lung cancer stages, greater brain metastases burden, and reduced overall survival (P < 0.05)." (PMID 40321254, 2025). "In this study, we evaluated the effect of two polymorphisms in the promoter regions of two human gelatinases, i.e., MMP-2 and MMP-9, on the risk of lung cancer development." (PMID 37445754, 2023). "Prior to examining the impact of these specific MMP-2-735C/T and MMP-9-1562C/T genotypes on the MMP-2 and MMP-9 concentrations, we performed logistic regression analyses to estimate the impact of each examined factor on the risk of lung cancer." (PMID 37445754, 2023). "The role of MMP-2-735C/T and MMP-9 -1562C/T polymorphisms in an increased risk of lung cancer cannot be dismissed." (PMID 37445754, 2023). "The reported results of the MMP-2-735C/T and MMP-9-1562C/T polymorphisms and their role in lung cancer risk are frequently conflicting." (PMID 37445754, 2023). "Foxp3 was also associated with upregulation of MMP2 and MMP9 in cholangiocarcinoma cells and lung cancer cells, EMT, and metastasis." (PMID 37766222, 2023). "The only significant association we observed was between age and the MMP-9-1562C/T genotype in lung cancer patients (p = 0.03854), with lung cancer patients with the CT and TT genotypes being found to be more often younger than those with the CC genotype." (PMID 37445754, 2023). "MSCs are known to cause transcriptional changes in lung cancer cells, leading to increased expression of MMP9." (PMID 35281822, 2022). "Elevated IL-6 levels above the reference threshold and a correlation between this cytokine and the metastatic biomarker MMP-9 indicate a higher risk of lung cancer aggressiveness." (PMID 34439874, 2021). "Overexpression of MMP2 and MMP9 has been linked to the progression of various types of cancer including lung cancer and correlates with cell invasion, metastasis, and poor prognosis." (PMID 34209215, 2021). "Previous studies have demonstrated a critical role of MMP9 in the progression of lung cancer and an association between MMP9 and poor survival in patients." (PMID 34988077, 2021). "Overexpression of both MMP2 and MMP9 is known to be associated with the progression of different types of cancer including lung cancer and correlates with metastasis and poor prognosis." (PMID 33958632, 2021). "The pharmacological inhibition of FAK phosphorylation was linked to reduced MMP-2 and MMP-9 expression and activation in breast and lung cancer cells." (PMID 32545852, 2020). "Here we uncover a role for MSC-mediated ABL tyrosine kinase-dependent activation of matrix metalloproteinase-9 (MMP9) in lung cancer cells which is linked to enhanced metastasis." (PMID 33119681, 2020). "In particular, alterations in TIMP-1 and MMP-9 levels have been observed in subjects with lung cancer compared to controls, associated with a poor prognosis, indicating a possible role of TIMP-1 and MMP-9 as a prognostic marker." (PMID 32392801, 2020). "Some promising results were obtained, which showed that subjects carrying the T allele were at a decreased risk of lung cancer in MMP9-1562C/T, and the C allele was associated with increased risk of developing lung cancer." (PMID 30889876, 2019). "Single nucleotide polymorphisms (SNP) in MMP-9 are significant predictors for lung cancer development and MMP-2 polymorphisms predict overall survival." (PMID 28915603, 2017). "Some studies have found a protective effect against digestive cancers and lung cancer for MMP-9 polymorphism, but its effects in prostate cancer vary." (PMID 29228747, 2017). "MMP2 and MMP9 are associated with lung cancer and can be secreted by cancer cells resulting in invasion and metastasis." (PMID 26759080, 2016).
lung carcinoma (continued). "MMP-9 is classically considered a ‘gelatinase’ involved in the breakdown of extracellular collagen matrix (ECM) protein and high levels of lung MMP-9 are associated with emphysema and lung cancer." (PMID 25615645, 2015). "ILK promotes lung cancer cell migration and invasion via upregulation of matrix metal-loproteinase-9 (MMP-9) and epithelial-mesenchymal transition-associated genes, including vimentin, fibronectin, Snail and Slug." (PMID 25760437, 2015). "Our data support the notion that the loss of miR-206 is associated with the up-regulation of MMP-9 level in lung cancer cells (A549 and SK-MES-1)." (PMID 26325180, 2015). "We found that the DLK1-promoted invasion of lung cancer cells was associated with upregulation of MMP9 expression and its extracellular activity, which are involved in ECM breakdown and highly associated with tumor invasion." (PMID 24621612, 2014). "In conclusion, our findings show a relationship between the MMP9 variant genotype and protection against the development of lung cancer and that the MMP2 variant genotype modifies the survival time in NSCLC patients." (PMID 22455335, 2012). "The variant genotype -1562 T/T in the MMP9 gene was associated with a decreased risk of developing lung cancer (adjusted OR = 0.23; 95% CI: 0.06-0.85; P = 0.027)." (PMID 22455335, 2012). "We have investigated the association between the -735 C/T, the -1171 5A/6A, and the -1562 C/T polymorphisms in the MMP2, MMP3 and MMP9 genes, respectively, and the risk and survival of lung cancer." (PMID 22455335, 2012). "Our results suggest that the studied polymorphism in the promoter region of the MMP9 gene is associated with the risk of the development of lung cancer." (PMID 22455335, 2012). "In other cancer forms, such as lung cancer, head and neck squamous cell carcinoma, and gastric cancer, MMP-9 associates with poor prognosis." (PMID 23216739, 2012). "These experimental analyses support the results obtained in our study where individuals with the MMP9 -1562 T/T genotype showed a decreased risk of developing lung cancer." (PMID 22455335, 2012). "In this study, we propose that fibronectin-induced stimulation of FAK that causes lung cancer cell migration and invasion occurs by the activation of MMP9/calpain-2 and MMP9/RhoA through the ERK and PI3K/Akt signalling pathways, respectively." (PMID 19568240, 2009). "Furthermore, both SP abundance and MMP-9 levels are significantly associated with advanced lung cancer stages, brain metastases, and poor survival outcomes." (PMID 40321254, 2025). "Associations are also found for MMP9 polymorphisms with lung cancer, COPD and asthma." (PMID 38166679, 2024). "In the previous decade, just five studies on the role of MMP-2 and MMP-9 polymorphism in lung cancer patients have been published and indexed in the MEDLINE (PubMed) database, which appears to be an understatement given the seriousness of the lung cancer problem." (PMID 37445754, 2023). "Importantly, we observed that both the decrease in the MMP-2 concentration and the increase in the MMP-9 concentration further enhance the risk of lung cancer development." (PMID 37445754, 2023). "We hypothesize that sublethal radiation activates EGFR and HER2, which subsequently up-regulates MMP-9 and associates with lung cancer cell survival and invasiveness." (PMID 32143669, 2020). "Of these proteases, the expression of MMP-2 and MMP-9 are associated with lung cancer progression." (PMID 32349289, 2020). "Furthermore, high activity of serum MMP‐9 and expression of MMP‐9 in the tumor tissue are significantly linked with lung cancer metastasis, tumor stage, and poor 5‐year overall survival rate." (PMID 32180962, 2020).